AGT (angiotensinogen)
Diseases named in the same sentence as AGT in open-access papers (continued):
Sharing a sentence is not in itself a finding about the gene and the disease.
primary hyperoxaluria type 1 (24 papers, 2009 to 2026). A rare disorder of glyoxylate metabolism characterized by the accumulation of oxalate due to a deficiency of the peroxisomal hepatic enzyme L-alanine: glyoxylate aminotransferase (AGT). "Here, we investigated the functional impact of modifying Ser81 in alanine:glyoxylate aminotransferase (AGT), the key enzyme responsible for glyoxylate detoxification and whose loss-of-function causes Primary Hyperoxaluria Type I (PH1)." (PMID 41979772, 2026). "A peculiar mechanism of mitochondrial mistargeting has also been reported in primary hyperoxaluria, in which mutations in alanine:glyoxylate aminotransferase (AGT) expose a cryptic MTS." (PMID 37283036, 2023). "Primary hyperoxaluria type I (PH1) is a rare metabolic disease caused by mutations in the AGXT gene causing loss-of-function in the alanine:glyoxylate aminotransferase (AGT) enzyme." (PMID 36557898, 2022). "Primary hyperoxaluria type 1 (PH1) is caused by defects in alanine:glyoxylate aminotransferase (AGT), resulting in systemic elevation of oxalate and accumulation of calcium oxalate precipitates in the kidney and other organs." (PMID 32455640, 2020). "Many pathogenic variants of AGT cause PH1 (primary hyperoxaluria type I), a rare autosomal recessive disorder." (PMID 28916765, 2017). "Deficiency in AGT function causes the accumulation of intracellular oxalate and the primary hyperoxaluria type 1 (PH1)." (PMID 27670739, 2016). "Primary Hyperoxaluria Type 1 (PH1) is a rare autosomal recessive kidney stone disease caused by deficiency of the peroxisomal enzyme alanine: glyoxylate aminotransferase (AGT), which is involved in glyoxylate detoxification." (PMID 24718375, 2014). "Primary hyperoxaluria type 1 (PH-1) is a recessive autosomal disease caused by a deficiency of hepatic peroxisomal alanine:glyoxylate aminotransferase (AGT; cofactor: pyridoxal phosphate), which catalyses the conversion of glyoxylate to glycine." (PMID 19247694, 2009). "Primary hyperoxaluria type 1 (PH1), the most common subtype of PH, results from a deficiency of the liver-specific enzyme alanine:glyoxylate aminotransferase (AGT), which is localized in peroxisomes." (PMID 41543738, 2026). "Primary hyperoxaluria type 1 (PH1) is a rare autosomal recessive metabolic disorder resulting from deficient hepatic alanine‐glyoxylate aminotransferase (AGT) activity, which is caused by mutations in the AGXT gene." (PMID 41275431, 2025). "Primary hyperoxaluria type 1 is a rare autosomal recessive disease of glyoxylate metabolism caused by a defect in the liver-specific peroxisomal enzyme alanine:glyoxylate aminotransferase (AGT) that leads to hyperoxaluria, recurrent urolithiasis, and nephrocalcinosis." (PMID 24934730, 2014). "Primary Hyperoxaluria Type 1 (PH1) is a severe autosomal recessive kidney stone disease, caused by loss or dysfunction of the enzyme alanine: glyoxylate aminotransferase (AGT)." (PMID 24718375, 2014). "To address this problem, we used, as model human peroxisomal alanine:glyoxylate aminotransferase (AGT), a dimeric pyridoxal 5′-phosphate (PLP)-dependent enzyme whose functional deficit causes primary hyperoxaluria type I (PH1)." (PMID 33917320, 2021). "This extended model was used in Ref.34 to compare wild-type cells (WT) and cells affected by the rare disease Primary Hyperoxaluria Type 1 (PH1), which lack alanine:glyoxylate aminotransferase (AGT) due to a genetic mutation." (PMID 30131869, 2018). "The situation has been most extensively studied for human AGT, since mistargeting from the peroxisomes to the mitochondria is involved in the rare disease known as primary hyperoxaluria type 1 (PH1)." (PMID 22558413, 2012). "One example is the association of mistargeting of the peroxisomal alanine:glyoxylate aminotransferase (AGT) to mitochondria with patients having primary hyperoxaluria type 1." (PMID 21548921, 2011).
primary hyperoxaluria type 1 (continued). "Primary hyperoxaluria type 1 (PH1) is a rare, autosomal recessive disease characterized by hepatic overproduction of oxalate due to a deficiency in the peroxisomal enzyme alanine–glyoxylate aminotransferase (AGT), which is encoded by the AGXT gene." (PMID 35913563, 2023). "Primary hyperoxaluria type I (PH1) is a rare kidney diseasedueto the deficit of alanine:glyoxylate aminotransferase (AGT), a pyridoxal-5′-phosphate-dependentenzyme responsible for liver glyoxylate detoxification, which in turnprevents oxalate formation and precipitation as kidney stones." (PMID 35830169, 2022). "Primary hyperoxaluria type 1 (PH1) is the most common and severe of the PHs, due to mutations in the AGXT gene (coding for AGT), with a high incidence of kidney failure as early as infancy." (PMID 39769031, 2024). "AGT deficiency, due to recessive pathogenic changes in the AGXT gene, results in calcium oxalate accumulation and kidney stones, a condition known as primary hyperoxaluria type 1 (PH1)." (PMID 40495747, 2025). "Primary hyperoxaluria type 1 (PH1, OMIM 259900) is a rare autosomal recessive disorder caused by a functional deficiency of the liver-specific peroxisomal enzyme alanine:glyoxylate aminotransferase (AGT, EC 2.6.1.44) due to mutations in the AGXT gene." (PMID 27670739, 2016). "Peroxisomal import is a key feature in the pathogenesis of primary hyperoxaluria type 1 (PH1), where alanine:glyoxylate aminotransferase (AGT) undergoes mitochondrial mistargeting in about a third of patients." (PMID 25689234, 2015). "Here we applied a computational approach to predict and analyze the metabolic alterations occurring in hepatocytes lacking alanine:glyoxylate aminotransferase (AGT), a peroxisomal enzyme encoded by the AGXT gene and mutated in primary hyperoxaluria type 1 (PH1)." (PMID 27239044, 2016).
Ureteral obstruction (24 papers, 2013 to 2025). Obstruction of the flow of urine through the ureter. "Experiments on fetal sheep demonstrated that fetal partial ureteral obstruction can cause upregulation of the levels of renin, angiotensinogen and angiotensin receptors, which result in water and salt retention." (PMID 32787795, 2020). "Exogenous Klotho expression suppressed the upregulation of AGT, renin, ACE, and AT1R protein expression and normalized blood pressure in 5/6 nephrectomised rats and unilateral ureteral obstruction (UUO) mice." (PMID 36059935, 2022). "In addition, ureteral obstruction attenuated the increase of AGT protein and Ang II in kidneys with podocyte injury, indicating that the major source of increased renal Ang II in podocyte injury is filtered AGT." (PMID 35710133, 2022).
Cachexia (23 papers, 2005 to 2026). Severe weight loss, wasting of muscle, loss of appetite, and general debility related to a chronic disease. "The metabolism of angiotensinogen to angiotensins found in the enrichment analysis involved nine low-level proteins that were considered to be related to cachexia caused by cancer." (PMID 40564899, 2025).
Cirrhosis (23 papers, 2007 to 2025). A chronic disorder of the liver in which liver tissue becomes scarred and is partially replaced by regenerative nodules and fibrotic tissue resulting in loss of liver function. "Interestingly, AGT production is upregulated in cirrhosis, despite a global reduction in other protein synthesis, and acts upon hepatic stellate cells (HSCs)." (PMID 38891995, 2024).
diabetic retinopathy (22 papers, 2011 to 2025). "A study in diabetic retinopathy rat models demonstrated that inhibition of angiotensinogen (AGT) using siRNA-AGT reduced activation of the Ang II–ERK1/2 signaling pathway, promoted proliferation, and decreased apoptosis of retinal endothelial cells." (PMID 41226756, 2025). "Genetic variations in genes such as angiotensinogen (AGT), angiotensin-converting enzyme (ACE), and angiotensin II receptor type 1 (AGTR1) have been associated with an increased risk of diabetic retinopathy." (PMID 38918766, 2024). "However, studies of vascular smooth muscle cell hypertrophy, coronary smooth muscle cells, diabetic retinopathy, etc. have reported p38MAPK signaling as another stimulus to increase angiotensinogen gene expression." (PMID 36647426, 2023).
hypertrophic cardiomyopathy (22 papers, 2009 to 2026). A condition in which the myocardium is hypertrophied without an obvious cause. "Some studies have reported that angiotensin converting enzyme (ACE) and angiotensinogen (AGT) genes have been associated with hypertrophic cardiomyopathy (HCM)." (PMID 24204726, 2013). "In addition, AGT M235T nucleotide transition is associated with sporadic hypertrophic cardiomyopathy (SHCM) rather than familial hypertrophic cardiomyopathy (FHCM) in which the mutations in sarcomeric genes have been found to be associated with the disease." (PMID 24204726, 2013).
lung carcinoma (22 papers, 2011 to 2025). "In conclusion, this meta-analysis provided statistical evidence supporting that the angiotensinogen Leu84Phe polymorphism was associated with increased risk of lung cancer, especially in Caucasian populations." (PMID 26376373, 2015). "There is evidence that angiotensinogen polymorphisms play a major role in lung cancer susceptibility among never-smokers, highlighting the importance to identify other potential susceptible agents for lung cancer in addition to smoking." (PMID 26376373, 2015). "Risk of lung cancer (odds ratio [OR] and 95% confidence interval [CI]) was estimated with the fixed or the random effects model assuming homozygous, allele, heterozygous, dominant, and recessive models for all angiotensinogen polymorphisms." (PMID 26376373, 2015). "A significant correlation between lung epithelial AGT expression and poor prognosis of lung cancer patients was also observed." (PMID 37258578, 2023). "We conclude that although KLF6 promotes AGT gene transcription when oncogenic K-Ras is expressed in normal cells, HMGA1 promotes AGT expression in lung cancer cells expressing oncogenic K-Ras." (PMID 33380422, 2021). "To validate our cell culture data in vivo, we assessed the expression of AGT in K-RasLA2-G12D mice, a model of lung cancer expressing oncogenic K-Ras." (PMID 33380422, 2021). "They found that the expression of angiotensinogen, the AngII precursor, was upregulated in a mouse model of lung adenocarcinoma as well as in human lung cancer stroma." (PMID 32582203, 2020). "What is the functional role of the AGT/Ang II/AT1-R pathway in lung cancer cells?" (PMID 33380422, 2021). "Interestingly, we find that expression of AGT remains elevated in lung cancer cells but in a Kruppel-like factor 6–independent and high-mobility group AT-hook 1–dependent manner." (PMID 33380422, 2021). "Finally, we find that expression of AGT is elevated in lung tumors of K-RasLA2-G12D mice, a mouse model of lung cancer, and human lung cancer." (PMID 33380422, 2021). "Finally, downregulation by siRNA of HMGA1, a positive regulator of AGT transcription in lung cancer cells, inhibited growth in soft agar of H460 cells." (PMID 33380422, 2021). "Downregulation of HMGA1 by siRNA inhibited AGT promoter activity in A549 lung cancer cells." (PMID 33380422, 2021). "A total of 10 articles were ultimately included after excluding the nongenetic association studies, and the genetic association studies not addressing the angiotensinogen polymorphisms and lung cancer." (PMID 26376373, 2015). "Earlier published studies investigating the association between polymorphisms in the angiotensinogen gene and lung cancer risk showed no consistent results." (PMID 26376373, 2015). "Moreover, the association between polymorphisms in the AGT and lung cancer risk showed no consistent results." (PMID 32090070, 2020). "When we overexpressed HMGA1 in HMGA1 siRNA-transfected lung cancer cells to restore HMGA1 expression, we rescued AGT promoter activity in these cells." (PMID 33380422, 2021). "Most components of the RAS including angiotensinogen, angiotensin-converting enzyme, ACE) and angiotensin receptors are expressed locally in a wide variety of tumors, including in lung cancers." (PMID 31133857, 2019). "Here, we tested the hypothesis that activation of STAT3 is the signaling pathway, downstream of the AGT/Ang II-mediated activation of the AT1-R, that fuels the transformed phenotype of lung cancer cells." (PMID 33380422, 2021). "In contrast to what we found in normal cells after overexpression of K-RasG12V, AGT expression was not mediated by the transcription factor KLF6 in lung cancer cells, in which KLF6 expression was dramatically downregulated." (PMID 33380422, 2021).
lung carcinoma (continued). "The concept that the lung possesses the machinery necessary for local Ang II synthesis is supported by data showing that treatment with bleomycin promotes AGT expression and Ang II synthesis in normal alveolar epithelial cells, A549 lung cancer cells, and lung myofibroblasts in cell culture studies." (PMID 33380422, 2021).
prostate carcinoma (21 papers, 2004 to 2025). A carcinoma that arises from epithelial cells of the prostate gland. "From a large genome-wide association study in patients with prostate cancer it was previously reported that SNPs tagging AGT, part of the renin-angiotensin system (RAS), correlated with patient-reported late hematuria, identifying a potential targetable pathway to prevent RT-induced bladder injury." (PMID 36400304, 2023). "If angiotensinogen is produced at higher levels in adjacent cells one ofthe activating enzymes which convert the product of the AGTgene in angiotensin II (ACE) is instead higher in PIN andL-PCA, suggesting the potential for utilization in tumour cells at lower stagesof prostate cancer development." (PMID 21479216, 2011).
dementia (19 papers, 2012 to 2025). Loss of intellectual abilities interfering with an individual's social and occupational functions. "We have found that none of the analysed polymorphisms in the genes of renin-angiotensin system, i.e. rs699, rs4762 in AGT, rs5186 in AGTR1, rs5194, rs1403543 in AGTR2 or ACE I/D was associated with MCI or dementia in Parkinson’s disease." (PMID 34302265, 2021).
glaucoma (19 papers, 2011 to 2025). Increased pressure in the eyeball due to obstruction of the outflow of aqueous humor. "Oxidative stress, a known etiology for glaucoma, induced the expression of prorenin and angiotensinogen in human TM cells." (PMID 32707887, 2020). "GO analysis revealed a large impact of glaucoma on positive regulation of cholesterol esterification as evidenced by the upregulation of angiotensinogen (AGT), apolipoprotein C-I (APOC1), and apolipoprotein A-IV (APOA4)." (PMID 27788204, 2016). "Analysis of AH samples from the cohort of POAG patients showed that AGT concentration did not change in glaucoma, whereas PEDF content increased dramatically with POAG progression, reaching approximately 10-fold excess at stage 3 of the disease." (PMID 40596696, 2025). "Moreover, human TM cells exposed to oxidative stress, a known etiology for glaucoma, selectively upregulated the RAPS ligand genes REN and AGT, while all the major RAPS components including their receptors were expressed at steady-state levels." (PMID 32707887, 2020).
renal hypertension (19 papers, 2012 to 2024). Hypertension caused by the kidney's hormonal response to narrowing or occlusion of the renal arteries. "In the present study, excessive activation of RAS was found in the PVN from renal hypertensive rats, as reflected by increased expression levels of AGT, Ang II, and AT1R." (PMID 28210225, 2017). "Compared with the values obtained for sham-operated rats, AGT, Ang II, and AT1R amounts in PVN from rats with renal hypertension were significantly higher (p < 0.05)." (PMID 28210225, 2017).
steatosis (18 papers, 2013 to 2025). Increased lipid within the cytoplasm of cells. "Last, the two RNA sequencing datasets were integrated to determine key processes that were altered by hepatic AGT deficiency during initiation of WD-induced steatosis." (PMID 40687776, 2025). "Surprisingly, despite the established protective effect against WD-induced steatosis, hepatocyte-specific AGT deficiency altered a select portion of the liver transcriptome, particularly genes related to metabolic and cell division processes, during the initiation phase of steatosis." (PMID 40687776, 2025). "The primary aim of this study was to identify previously unknown molecules that may interact with AGT during the initiation phase of steatosis." (PMID 40687776, 2025). "Afamin (AFM), angiotensinogen (AGT), β-defensin 1 (DEFB1), and PRAP1 were correlated with steatosis; DEFB1 was correlated with the NAS; and 90 proteins were associated with hepatocyte ballooning." (PMID 40250425, 2025). "However, the effects of hepatic AGT deficiency were not mimicked by pharmacological inhibition of the RAS, and the molecular mechanisms by which AGT deficiency protects against WD-induced steatosis is unknown." (PMID 40687776, 2025).
vascular hypertrophy (18 papers, 2012 to 2024). "AT1 receptor antagonism is renoprotective, abrogating the effects of Ang II on oxidative stress, intrarenal formation of angiotensinogen and renin, inflammation, vascular hypertrophy, renal dysfunction, proteinuria, and HTN." (PMID 39765782, 2024).
vitamin D deficiency (18 papers, 2013 to 2025). A nutritional condition produced by a deficiency of VITAMIN D in the diet, insufficient production of vitamin D in the skin, inadequate absorption of vitamin D from the diet, or abnormal conversion of vitamin D to its bioactive metabolites. "Vitamin D deficiency has been shown to activate RAS and knockout mice for VDR‐caused renin overexpression, resulting in more angiotensinogen transformed into angiotensin II." (PMID 34950831, 2021).
renal dysfunction (17 papers, 2009 to 2025). "We analyzed single nucleotide polymorphisms (SNPs) associated with cardiovascular pathophysiology (including AGT1R T573C, AGT1R A1166C, and AGT M235T) and presence of renal dysfunction (eGFR<60 ml/min/1.73 m2) or history of CHD." (PMID 19327134, 2009). "Regarding RAAS and renal dysfunction markers, in the overall study population, admission values of u-CysLT showed a borderline positive correlation with u-AGT, a marker of intrarenal RAAS activation, which in turn also had a borderline significant positive correlation with u-Isop." (PMID 36359365, 2022).
anemia (15 papers, 2005 to 2025). A reduction in the number of red blood cells, the amount of hemoglobin, and/or the volume of packed red blood cells. "The anemia of angiotensinogen-knockout mice was rescued by ATII infusion, suggesting that a genetic pathway from angiotensinogen to ATII plays a key role in ATII-induced Epo production." (PMID 34500833, 2021). "Here we report that knockout mice that lack angiotensin II, including angiotensinogen and renin knockout mice, exhibit anemia." (PMID 26107632, 2015). "The anemia of angiotensinogen knockout mice was rescued by angiotensin II infusion, and rescue was completely blocked by simultaneous administration of AT1 receptor blocker." (PMID 26107632, 2015).
asthma (15 papers, 2009 to 2025). "Notable genes that were differentially methylated based on asthma severity included RUNX3, several members of the HLA family, AGT, PTPRC, PTPRJ, and several genes downstream of the JAK2 and TNF signaling pathway." (PMID 39380119, 2024). "IPA analyses of increased abundance of the four proteins (MMP9, AGT, S100A8, CTSC) in the POLD group (when compared to PTc) suggested increased neutrophil accumulation, which is a reasonable hypothesis given the association of neutrophilic inflammation with wheezing in asthma." (PMID 37474963, 2023).
coagulopathy (13 papers, 2014 to 2024). "Functional SNPs in these genes and their action may be exaggerated by coagulopathies (ACE, AGT) or by apoptosis (STAT1)." (PMID 25264875, 2014).